RORA (RAR related orphan receptor A)
Description:
Nuclear receptor that binds DNA as a monomer to ROR response elements (RORE) containing a single core motif half-site 5'-AGGTCA-3' preceded by a short A-T-rich sequence. Key regulator of embryonic development, cellular differentiation, immunity, circadian rhythm as well as lipid, steroid, xenobiotics and glucose metabolism. Considered to have intrinsic transcriptional activity, have some natural ligands like oxysterols that act as agonists (25-hydroxycholesterol) or inverse agonists (7-oxygenated sterols), enhancing or repressing the transcriptional activity, respectively. Recruits distinct combinations of cofactors to target genes regulatory regions to modulate their transcriptional expression, depending on the tissue, time and promoter contexts. Regulates genes involved in photoreceptor development including OPN1SW, OPN1SM and ARR3 and skeletal muscle development with MYOD1. Required for proper cerebellum development. Regulates SHH gene expression, among others, to induce granule cells proliferation as well as expression of genes involved in calcium-mediated signal transduction. Regulates the circadian expression of several clock genes, including CLOCK, BMAL1, NPAS2 and CRY1. Competes with NR1D1 for binding to their shared DNA response element on some clock genes such as BMAL1, CRY1 and NR1D1 itself, resulting in NR1D1-mediated repression or RORA-mediated activation of clock genes expression, leading to the circadian pattern of clock genes expression. Therefore influences the period length and stability of the clock. Regulates genes involved in lipid metabolism such as apolipoproteins APOA1, APOA5, APOC3 and PPARG. In liver, has specific and redundant functions with RORC as positive or negative modulator of expression of genes encoding phase I and phase II proteins involved in the metabolism of lipids, steroids and xenobiotics, such as CYP7B1 and SULT2A1. Induces a rhythmic expression of some of these genes. In addition, interplays functionally with NR1H2 and NR1H3 for the regulation of genes involved in cholesterol metabolism. Also involved in the regulation of hepatic glucose metabolism through the modulation of G6PC1 and PCK1. In adipose tissue, plays a role as negative regulator of adipocyte differentiation, probably acting through dual mechanisms. May suppress CEBPB-dependent adipogenesis through direct interaction and PPARG-dependent adipogenesis through competition for DNA-binding. Downstream of IL6 and TGFB and synergistically with RORC isoform 2, is implicated in the lineage specification of uncommitted CD4(+) T-helper (T(H)) cells into T(H)17 cells, antagonizing the T(H)1 program. Probably regulates IL17 and IL17F expression on T(H) by binding to the essential enhancer conserved non-coding sequence 2 (CNS2) in the IL17-IL17F locus. Involved in hypoxia signaling by interacting with and activating the transcriptional activity of HIF1A. May inhibit cell growth in response to cellular stress. May exert an anti-inflammatory role by inducing CHUK expression and inhibiting NF-kappa-B signaling.
Synonyms: NR1F1; RZRA; ROR1; ROR2; ROR3; ROR-alpha; RORalpha; RORa1; RORα; IDDECA; RZR-ALPHA
Tractability: Small molecule: a structure with a bound ligand is known; a high-quality ligand is known; it has a binding pocket of medium quality; it belongs to a druggable protein family. PROTAC: UniProt records ubiquitination sites on it; ubiquitination databases record sites on it; a small molecule that binds it is known.
Target class: Nuclear hormone receptor subfamily 1 group F; Nuclear hormone receptor subfamily 1; Nuclear receptor; Nuclear hormone receptor subfamily 1 group F member 1; Transcription factor
Chemical probes: ML124, SR3335, TO-901317 (high quality)
Gene: Protein-coding gene on chromosome 15 (60,488,284 to 61,229,302, reverse strand). Ensembl gene ENSG00000069667.
Subcellular location: Nucleus
Subcellular location (Human Protein Atlas): Nucleoli
Pathways (Reactome):
Circadian clock: Expression of BMAL (ARNTL), CLOCK, and NPAS2; Phosphorylated BMAL1:CLOCK (ARNTL:CLOCK) activates expression of core clock genes; Phosphorylation of CLOCK, acetylation of BMAL1 (ARNTL) at target gene promoters; RORA,B,C and NR1D1 (REV-ERBA) regulate gene expression; The CRY:PER:kinase complex represses transactivation by the BMAL:CLOCK (ARNTL:CLOCK) complex
Cellular responses to stimuli: Heme signaling
Gene expression (Transcription): Nuclear Receptor transcription pathway
Immune System: Interleukin-4 and Interleukin-13 signaling
Metabolism: PPARA activates gene expression
Metabolism of proteins: SUMOylation of intracellular receptors
Gene Ontology:
Molecular function: DNA binding; DNA-binding transcription factor activity; ligand-modulated transcription factor activity; oxysterol binding; protein binding; RNA polymerase II cis-regulatory region sequence-specific DNA binding; RNA polymerase II transcription regulatory region sequence-specific DNA binding; sequence-specific DNA binding; transcription coactivator binding; transcription coregulator binding; transcription corepressor binding; DNA-binding transcription factor activity, RNA polymerase II-specific; nuclear receptor activity; beta-catenin binding; zinc ion binding
Biological process: angiogenesis; cellular response to hypoxia; cellular response to sterol; intracellular receptor signaling pathway; muscle cell differentiation; negative regulation of canonical NF-kappaB signal transduction; negative regulation of inflammatory response; positive regulation of DNA-templated transcription; positive regulation of transcription by RNA polymerase II; positive regulation of vascular endothelial growth factor production; regulation of DNA-templated transcription; triglyceride homeostasis; cerebellar granule cell precursor proliferation; cholesterol homeostasis; circadian regulation of gene expression; negative regulation of fat cell differentiation; positive regulation of circadian rhythm; regulation of glucose metabolic process; regulation of smoothened signaling pathway; regulation of steroid metabolic process; regulation of transcription by RNA polymerase II; xenobiotic metabolic process; regulation of circadian rhythm; regulation of gene expression; T-helper 17 cell differentiation
Cellular component: nucleolus; nucleus; chromatin; nucleoplasm
Genetic constraint (gnomAD): Loss-of-function variants: 4 observed, 44.28 expected, observed/expected ratio (o/e) 0.0903, 90% interval 0.043 to 0.21. The upper end of that interval is the gene's LOEUF score, 0.21, which puts it in group 1 of 6, group 1 being the genes least tolerant of losing a copy. Missense variants: 342 observed, 481.71 expected, observed/expected ratio (o/e) 0.71, 90% interval 0.65 to 0.78. Synonymous variants: 200 observed, 181.43 expected, observed/expected ratio (o/e) 1.1, 90% interval 0.98 to 1.24.
Homologues: Orthologues: dog RORA (99% identical), rat Rora (97% identical), rabbit RORA (90% identical), chimpanzee RORA (89% identical), macaque RORA (89% identical), guinea pig RORA (88% identical), pig RORA (88% identical), mouse Rora (87% identical), tropical clawed frog rora (81% identical), zebrafish roraa (80% identical), Caenorhabditis elegans nhr-23 (32% identical), Caenorhabditis elegans sex-1 (22% identical), and 183 more. Paralogues in human: RORB (56% identical), RORC (49% identical), NR1D2 (28% identical), NR1D1 (27% identical), RARB (27% identical), RARG (27% identical), RARA (25% identical), THRB (23% identical), PPARG (23% identical), PPARA (22% identical), THRA (21% identical), PPARD (21% identical), and 6 more.
Diseases named in the same sentence as RORA in open-access papers:
RORA is named in the same sentence as 232 diseases in open-access papers, as found by Europe PMC text mining. Sharing a sentence is not in itself a finding about the gene and the disease. The quoted sentences say what the papers report.
breast carcinoma (49 papers, 2010 to 2025). "For instance, elevated RORA expression has been associated with increased invasiveness and poor prognosis in specific breast cancer subtypes." (PMID 40638694, 2025). "In our previous studies, we have determined that poor clinical outcomes in breast cancer patients are linked to the downregulation of RORα." (PMID 38791992, 2024). "Our previous studies have shown that a loss of RORα is associated with enhanced breast cancer malignancy, cell invasion and proliferation, epithelial–mesenchymal transition, and cancer-associated inflammation." (PMID 38791992, 2024). "We recently reported that reduced RORα expression in breast cancer tissue is associated with a high incidence of cancer metastasis, and that RORα expression significantly inhibits spreading of metastatic breast cancer cells to distant organs." (PMID 35605663, 2022). "This evidence suggests the potential function of RORα in inflammation; however, the exact roles of RORα in breast cancer-associated inflammation and macrophage infiltration remain to be determined." (PMID 34639006, 2021). "We showed previously that reduced RORα expression was associated with poor prognosis in breast cancer patients." (PMID 34639006, 2021). "In the present study, we showed that RORα expression inhibited ROS generation, cancer-associated macrophage infiltration, and breast cancer metastasis." (PMID 34639006, 2021). "We showed that RORα expression was negatively associated with mRNA levels of complex I genes in human breast cancer tissues." (PMID 34639006, 2021). "We also found that RORα expression inhibited cancer-associated macrophage infiltration and breast cancer metastasis in vivo." (PMID 34639006, 2021). "The loss of RORA gene copy number was detected in 30% of human breast cancer tissue and is associated with reduced gene transcription." (PMID 34639006, 2021). "We showed that the expression of mitochondrial complex I genes was negatively associated with RORα levels in human breast cancer tissues." (PMID 34639006, 2021). "Reduced RORα expression has been observed in colorectal and mammary carcinomas and found to be associated with poorer prognosis in hepatocellular and breast carcinoma patients." (PMID 26878025, 2015). "Both genes had been implicated as targets of RORA by earlier studies with Rora-deficient mice as well as in human breast cancer." (PMID 23697635, 2013). "Therefore, the prevention of RORα loss or downregulation is a pathway to prevent breast cancer initiation and progression." (PMID 38791992, 2024). "RORα polymorphisms correlate with human diseases such as breast cancer and asthma." (PMID 35309302, 2022). "Interestingly, we found that the higher ratio of RORα/Snail mRNA level in breast cancer tissues was associated with longer recurrence-free survival." (PMID 35605663, 2022). "In addition, RORα polymorphisms correlate with different diseases, such as multiple sclerosis, breast cancer, asthma in human patients." (PMID 35309302, 2022). "In addition, reduced RORα expression in breast cancer tissue was associated with an increased incidence of cancer metastasis." (PMID 34639006, 2021). "Notably, low levels of RORα mRNA in breast cancer tissue are associated with short metastasis-free survival." (PMID 34639006, 2021). "Restoration of RORα expression in breast cancer cells resulted in morphologic characteristics associated with less aggressive tumor types: non-branched round spheroid structures in 3D culture, with a colony size and invasive capacity that was significantly reduced." (PMID 23443091, 2012). "RORA gene expression has been associated with decreased proliferation and invasion because it inhibits the Wnt/β-catenin pathway, preventing the transformation and progression of some types of cancer, such as breast cancer and negatively regulates genes such as c-jun, c-myc and cyclin D1." (PMID 39010137, 2024).
breast carcinoma (continued). "Studies using the gene set analysis method confirmed an association with ARNTL, CLOCK, and RORA and additionally reported an association with RORB, RORC, CRY, and the overall pathway in relation to breast cancer risk." (PMID 40534841, 2025). "In the myeloid compartment, metastatic breast cancer patients show enrichments of inflammatory monocytes characterised by high RORA, MYL9 and ITGB5 transcription." (PMID 40340807, 2025). "Polymorphisms in CLOCK, NPAS2, CRY2, RORA, TIMELESS, and ARNTL have been associated with breast cancer." (PMID 40534841, 2025). "In breast cancer cells, the expression of RORα significantly inhibits Snail transcription by binding RORα to ROREs in the promoter region of the Snai1 gene." (PMID 41425709, 2025). "When PRMT5 is silenced in mammary epithelial cells, RORα protein is degraded and downregulated, and it consequently promotes mammary epithelial cells into transforming and initiating breast cancer." (PMID 38791992, 2024). "Several studies suggest that RORα expression is down-regulated during tumor development and progression, while exogenous RORα inhibits cell proliferation and tumor growth in colorectal, prostate and breast cancer." (PMID 39201396, 2024). "RORα has been reported as a potential tumor suppressor in solid tumors, including breast cancer, lung cancer, melanoma, colon cancer, hepatocellular carcinoma, prostate cancer, and glioma." (PMID 38791992, 2024). "In the future, it will be important to examine the correlation between nuclear PRMT5 and RORα in human breast cancer tissue." (PMID 38791992, 2024). "A decreased expression of RORα in breast cancer fosters invasion and proliferation, enhances epithelial–mesenchymal transition (EMT), and triggers cancer-associated inflammation in the tumor microenvironment." (PMID 38791992, 2024). "RORA, one of the circadian genes, inhibited tumorigenesis and progression in various tumors, including breast cancer, prostate cancer, lung carcinoma, endometrial cancer, and gastric cancer." (PMID 37543714, 2023). "One potential explanation is that Snail expression in breast cancer tissue is regulated by multiple factors; RORα is only one of these factors." (PMID 35605663, 2022). "We and others have identified RORα as a potential tumor suppressor in colon cancer, hepatocellular carcinoma, prostate cancer, glioma, and breast cancer." (PMID 35605663, 2022). "The upregulation of TIMELESS has also been found in cervical carcinoma, colorectal cancer, and breast cancer, and the downregulation of RORA has been found in many cancers including hepatocellular carcinoma, gastric cancer, melanoma, and breast cancer." (PMID 35078435, 2022). "In the present study, we showed that retinoid orphan nuclear receptor alpha (RORα) significantly decreased ROS levels and inhibited ROS-mediated cytokine expression in breast cancer cells." (PMID 34639006, 2021). "We found that the expression of RORα in these breast cancer cell lines significantly reduced the number of invasive branches and suppressed invasive tumor growth in 3D culture." (PMID 34639006, 2021). "We found that expressing RORα in breast cancer cells significantly decreased the number of THP-1 or differentiated THP-1 cells that migrated into the lower chamber." (PMID 34639006, 2021). "RORα was identified as a potential tumor suppressor in breast cancer; however, the molecular and cellular mechanisms by which it suppresses cancer progression are not fully understood." (PMID 34639006, 2021). "Previous studies identified retinoid orphan nuclear receptor alpha (RORα) as a potential tumor suppressor in human breast cancer." (PMID 34639006, 2021). "The results from the co-culture experiments suggest that RORα inhibits macrophage accumulation in breast cancer tissue at least partially through IL-6 repression." (PMID 34639006, 2021).
breast carcinoma (continued). "In the present study, we showed that the downregulation of RORα in breast cancer cells induced ROS generation by enhancing complex I gene expression." (PMID 34639006, 2021). "To determine how RORα regulates ROS generation and cytokine expression, we performed gene co-expression analysis using the breast cancer TCGA dataset." (PMID 34639006, 2021). "To determine how RORα expression is regulated during breast cancer development, we analyzed DNA copy number at RORA gene loci." (PMID 34639006, 2021). "Besides, Du and Xu observed that RORA suppressed the expression of malignant phenotypes in breast cancer cell lines both in vitro and in vivo, which indicated that RORA could be considered an ideal potential diagnostic biomarker and therapeutic target of breast cancer." (PMID 32802855, 2020). "In breast tumors, RORα suppresses tumor progression by inducing cell polarization and inhibiting cell invasion, which provides a potential therapeutic target for breast cancer." (PMID 33336001, 2020). "NSW increased risk of breast cancer in women who carried the heterozygote genotype of CRY2 rs2292912 (OR = 1.98, 95% CI = 1.14–3.44) or carried at least one minor allele of RORA rs1482057 (OR = 2.20, 95% CI = 1.10–4.37)." (PMID 31358835, 2019). "RORα has been identified as a potential therapeutic target for breast cancer and has been investigated in melanoma, colorectal colon cancer, and gastric cancer." (PMID 29904382, 2018). "Recent studies suggest the potential role of RORα in progression and prognosis of cancer including colon cancer and breast cancer, and that RORα functions as suppression of tumor cell proliferation and augmentation of apoptosis." (PMID 28052040, 2017). "Increased RORα expression suppressed also the aggressive phenotype in breast cancer models, including reduced colony size, inhibited cell proliferation, invasion and migration." (PMID 27542227, 2016). "It was proposed that the increase in aromatase expression by RORα accelerates the local production of estrogen, which then enhances the proliferation of breast cancer cells." (PMID 26878025, 2015). "Conversely, restoring RORα expression in cultured breast cancer cells was shown to inhibit cell migration and suppress tumor growth and metastasis in nude mice." (PMID 26878025, 2015). "In contrast to its growth inhibitory effects, RORα was shown to enhance the proliferation in mammary carcinoma MCF7 cells and significantly induced the expression of aromatase mRNA by binding an RORE in the aromatase promoter region." (PMID 26878025, 2015). "Expression of RORα in breast cancer cells significantly induces SEMA3F transcription and inhibits the mammary tumor invasion in 3D culture." (PMID 23443091, 2012). "Since disruption of polarized acinar structure is an important early event for breast cancer development, this study suggested that reduced RORα expression contributes to the earliest stages of breast cancer development." (PMID 23443091, 2012). "Hopefully, RORα-specific, clinically-useful agonists for breast cancer treatment will be identified and tested in the future." (PMID 23443091, 2012). "MCF-7 breast cancer cells show similar results when RORα is overexpressed; a significant increase in sub-G1 cells relative to control cells (15.5% vs 4.5%)." (PMID 22509368, 2012). "This information suggests that RORα is a potent tumor suppressor and a potential therapeutic target for breast cancer." (PMID 23443091, 2012). "While RORα mRNA has been detected in both ER-positive and ER-negative human breast cancer cells, the RORα gene appears to be down-regulated in breast cancer compared to normal mammary tissue." (PMID 23443091, 2012). "RORα is commonly down-regulated and/or hypoactivated in breast cancer compared to normal mammary tissue." (PMID 23443091, 2012). "It has been shown that RORα cooperates with ER to induce cyclin D1 expression in the ER-positive breast cancer cell line MCF-7." (PMID 23443091, 2012).